MIR601 (microRNA 601)
Synonyms: hsa-mir-601; MIRN601
Gene: MicroRNA gene on chromosome 9 (123,402,525 to 123,402,603, reverse strand). Ensembl gene ENSG00000207991.
Gene Ontology:
Biological process: miRNA-mediated post-transcriptional gene silencing
Cellular component: RISC complex
Diseases named in the same sentence as MIR601 in open-access papers:
MIR601 is named in the same sentence as 1 disease in open-access papers, as found by Europe PMC text mining. Sharing a sentence is not in itself a finding about the gene and the disease.
MIR601 shares sentences with these, for which no sentence is quoted: infection (1 paper).